RNU6-1311P (RNA, U6 small nuclear 1311, pseudogene)
Gene: Small nuclear RNA gene on chromosome 5 (134,634,839 to 134,634,945, reverse strand). Ensembl gene ENSG00000207459.
Homologues: Orthologues: chimpanzee U6 (99% identical), macaque U6 (91% identical), guinea pig U6 (87% identical), dog U6 (66% identical). Paralogues in human: RNU6-11P (88% identical), RNU6-1310P (88% identical), RNU6-1316P (88% identical), RNU6-24P (88% identical), RNU6-333P (88% identical), RNU6-37P (88% identical), RNU6-43P (88% identical), RNU6-560P (88% identical), RNU6-86P (88% identical), RNU6-1083P (87% identical), RNU6-1091P (87% identical), RNU6-20P (87% identical), and 1287 more.